RAB39B (RAB39B, member RAS oncogene family)
Diseases named in the same sentence as RAB39B in open-access papers (continued):
Sharing a sentence is not in itself a finding about the gene and the disease.
Macrocephaly (7 papers, 2012 to 2025). Occipitofrontal (head) circumference greater than 97th centile compared to appropriate, age matched, sex-matched normal standards. "The in vivo roles of RAB39b, a known small GTPase gene associated with X-linked ASD and macrocephaly, were investigated through Rab39b knockout mice and RAB39b-mutated human PSCs." (PMID 34886158, 2021).
autism spectrum disorder (6 papers, 2015 to 2022). A spectrum of developmental disorders that includes autism, and Asperger syndrome. "Indeed, in the absence of RAB39B, AMPARs arrangement at the post-synaptic site is misregulated, which provides an explanation for the involvement of RAB39B mutations in the aetiology of ID and autism spectrum disorder." (PMID 25784538, 2015).
X-linked intellectual disability (6 papers, 2020 to 2023). An X-linked intellectual deficiency in which not enough information is known, reported or published to indicate whether a gene causes non-syndromic or syndromic presentations. "Loss-of-function mutations in the RAB39B gene, which encodes a neuronal-specific small GTPase RAB39B, have been associated with X-linked intellectual disability and pathologically confirmed early-onset PD in multiple families." (PMID 36761179, 2023). "Mutations in RAB39B gene are associated with a variety of neurological disorders including X-linked intellectual disability (XLID), autism, epilepsy, macrocephaly and early-onset Parkinson’s disease (EOPD)." (PMID 36761179, 2023).
Anxiety (4 papers, 2013 to 2023). Intense feelings of nervousness, tension, or panic often arise in response to interpersonal stresses. "However, Rab39b deficiency led to reduced anxiety and impaired learning and memory in 2 months old mice." (PMID 33364235, 2020). "However, in high elevated plus maze tests, Rab39b KO mice spent more time in the open arms than WT littermates, implying that loss of Rab39b reduced mouse anxiety." (PMID 33364235, 2020). "Rab39b KD mice showed behaviour comparable to that of WT mice when analyzing the variables assessing anxiety-like behaviour, such as time spent in the dark compartment in the dark & light test and time spent in the home box in the emergence test." (PMID 34761259, 2022). "The behavioural assessment of Rab39b KD mice revealed normal anxiety-like, exploratory and motivational behaviour." (PMID 34761259, 2022). "Consistently, in high elevated plus maze tests and light–dark transition tests, neuronal overexpression of RAB39B did not alter the anxiety and locomotor activity of both male and female mice." (PMID 36977207, 2023).
diffuse large B-cell lymphoma (3 papers, 2022 to 2025). "RAB39B is associated with proliferation, apoptosis and drug sensitivity of diffuse large B-cell lymphoma (DLBCL), the most common aggressive lymphoma." (PMID 36902149, 2023). "Research indicates that RAB39B exhibits increased expression in various types of tumors, such as germ cell tumors, gastric stromal tumors, and diffuse large B-cell lymphoma." (PMID 40177653, 2025). "According to reports, cancer researchers have found a high expression of Rab39B in germ cell tumors, gastric stromal tumors, and diffuse large B-cell lymphomas." (PMID 40177653, 2025).
Waisman syndrome (3 papers, 2021 to 2024). "Notably, GDI1 has been associated with Intellectual developmental disorder, X-linked 41 (OMIM # 300,849), and RAB39B has been linked to Intellectual developmental disorder, X-linked 72 (OMIM # 300,271) and Waisman syndrome (OMIM # 311,510)." (PMID 38373942, 2024).
dementia (2 papers, 2021 to 2022). Loss of intellectual abilities interfering with an individual's social and occupational functions. "Here, analysis of the spatial distribution and expression of RAB39B was conducted in post‐mortem human brain tissue from cases of dementia with Lewy bodies (DLB, n = 10), Alzheimer’s disease (AD, n = 12) and controls (n = 12)." (PMID 32762091, 2021). "Moreover, marked accumulation of Rab39b in Amyloid β (Aβ) plaques and a subset of LB in parallel with a marked reduction in Rab39b in the white matter regions were reported in the brains of patients affected by dementia with LB (DLB)." (PMID 36009486, 2022).
Lewy body diseases (2 papers, 2021 to 2023). "Thus RAB39B, its associated functional pathways and its entrapment in aggregates may be considered as future targets for therapeutic interventions to impede the overall pathological burden and cellular dysfunction in Lewy body diseases." (PMID 32762091, 2021).
synucleinopathies (2 papers, 2019 to 2024). "PD patients with PRKN and RAB39B mutations commonly exhibited α-syn (synucleinopathy) and AT8 (p-tau) positivity." (PMID 38751879, 2024). "Furthermore, tauopathies were observed in PD patients with RAB39B and PRKN mutations prior to the development of synucleinopathies, suggesting that tau accumulation may be upstream of α-syn aggregates." (PMID 38751879, 2024). "In conclusion, our study of peripheral cutaneous synucleinopathy characteristics in patients with genetic PD yielded several key findings: (i) P-α-syn was deposited in the peripheral cutaneous nerves of PD patients with CHCHD2, LRRK2, or GBA mutations but not in those with RAB39B or PRKN mutations." (PMID 38751879, 2024).
acute myeloid leukemia (1 paper, 2025). Acute myeloid leukemia (AML) is a group of neoplasms arising from precursor cells committed to the myeloid cell-line differentiation. "The objective of this research was to investigate the involvement of RAB39B in acute myeloid leukemia (AML) using bioinformatics analysis and in vitro experiments for validation." (PMID 40177653, 2025).
amyotrophic lateral sclerosis (1 paper, 2021). Amyotrophic lateral sclerosis (ALS) is a neurodegenerative disease characterized by progressive muscular paralysis reflecting degeneration of motor neurons in the primary motor cortex, corticospinal tracts, brainstem and spinal cord. "Furthermore, via its interaction with the chromosome 9 open reading frame 72 (C9orf72) gene product, implicated in amyotrophic lateral sclerosis (ALS) and frontotemporal dementia (FTD), additional roles for RAB39B in postsynaptic GluR subunit expression and autophagy have also been established." (PMID 32762091, 2021).
chlamydial infection (1 paper, 2019). "Our results show that chlamydial infection did not alter the distribution of Rab39a at the late endocytic pathway and Rab39b at the early secretory route." (PMID 30987349, 2019).
cholangiocarcinoma (1 paper, 2022). A carcinoma that arises from the intrahepatic biliary tree (intrahepatic cholangiocarcinoma) or from the junction, or adjacent to the junction, of the right and left hepatic ducts (hilar cholangiocarcinoma). "CHOL (cholangiocarcinoma), HNSC (head and neck squamous cell carcinoma), and PRAD (prostate adenocarcinoma) had significantly higher expression of RAB39B than adjacent normal tissues." (PMID 35910358, 2022).
Down syndrome (1 paper, 2022). "In 14 patients, the presence of Lewy bodies was examined, with positive findings in six cases (42.9%): 22q11.2 deletion syndrome (n = 2/3), Down syndrome (n = 2/2), NR4A2 (n = 1/1) and RAB39B (n = 1/1)." (PMID 36699000, 2022).
Fanconi anemia (1 paper, 2025). Fanconi anemia (FA) is a hereditary DNA repair disorder characterized by progressive pancytopenia with bone marrow failure, variable congenital malformations and predisposition to develop hematological or solid tumors. "According to the KEGG functional annotation, RAB39B and its associated genes primarily participate in the Wnt signaling pathway, Fanconi anemia pathway, T-cell receptor signaling pathway, and phosphatidylinositol signaling pathway." (PMID 40177653, 2025).
Sleep apnea (1 paper, 2023). An intermittent cessation of airflow at the mouth and nose during sleep is known as sleep apnea. "The results showed that Lasso regression identified a total of seven genes as the characteristic genes of sleep apnea, which are: C12orf54, FOS, GPR1, OR9A4, MYO5B, RAB39B, KLHL4, as the core genes of follow-up research and construction of prediction models." (PMID 38077447, 2023).
X-linked Parkinson’s disease (1 paper, 2023). "Rab39b, which has been reported to regulate alpha-synuclein accumulation and has loss-of-function mutations in X-linked Parkinson’s disease, was strongly depleted in VPS35 KO lysosomes." (PMID 37248224, 2023).
cancer (6 papers, 2011 to 2025). A tumor composed of atypical neoplastic, often pleomorphic cells that invade other tissues. "An example is represented by Rab39, with Rab39a implicated in cancer and Rab39b in PD." (PMID 31426400, 2019). "Through the examination of information obtained from accessible databases, we assessed the variation in RAB39B expression in both pan-cancer and AML." (PMID 40177653, 2025). "Through analysis of TCGA data, we found that RAB39B has significant expression differences in most cancers and AMLs of pan-cancer." (PMID 40177653, 2025). "The TIMER database was used to analyze the mRNA levels of RAB39B in tumors and adjacent normal tissues in pan-cancer." (PMID 35910358, 2022). "In cancer research, RAB39B is reported to be upregulated in germ cell neoplastic and gastric stromal tumors." (PMID 35910358, 2022). "Emerging evidence also highlights Rab39B’s potential role in intracellular vesicle trafficking and signaling pathways related to cancer cell proliferation, migration, and invasion, suggesting it may represent a novel therapeutic target." (PMID 40177653, 2025). "A notable variation in RAB39 expression was observed among 26 cancer types, including AML (LAML), when comparing the expression of RAB39B in normal and tumor samples from TCGA and GTEx databases." (PMID 40177653, 2025). "The rationale for the selection of the genes, HKDC1, RAB3IL1, RAB39B, FTH1, and FAM213A, is their potential pro-tumorigenic roles in other cancer types." (PMID 37082446, 2023). "We also observed the enrichment of several cancer-related pathways, like cytokine–cytokine receptor interaction, JAK-Stat signaling pathway, and NF-Kappa B signaling pathway, using the KEGG pathway enrichment analysis of RAB39B co-expressed genes." (PMID 35910358, 2022).
neurodegenerative disease (4 papers, 2020 to 2022). A disorder of the central nervous system characterized by gradual and progressive loss of neural tissue and neurologic function. "Since RAB39B mutations are also associated with the neurodegenerative disease PD, the age-dependent changes in Rab39b KO mice and whether these changes can be reversed by modulating autophagy and/or glutamate receptors warrant further scrutiny." (PMID 33364235, 2020). "Thus, dysfunctions in RAB39B trafficking as a consequence of age‐associated protein aggregation may well contribute to an array of neurodegenerative diseases." (PMID 32762091, 2021). "Despite evidence linking RAB39B to neurodegeneration, the involvement of the protein in idiopathic neurodegenerative diseases remains undetermined." (PMID 32762091, 2021).
neurodevelopmental disorder (3 papers, 2021 to 2024). A behavioral and cognitive disorder with onset during the developmental period that involves impaired or aberrant development of intellectual, motor, or social functions. "The pathogenicity of mutations causing the downregulation of RAB39B proteins, impacting AMPAR trafficking and dendritic spine morphogenesis, reinforced the idea that AMPAR modulation and dendritic spine assets could be considered hallmarks of neurodevelopmental disorders." (PMID 34761259, 2022). "This indicates that the absence of RAB39B and the final amount of increased Ca2+-permeable AMPARs on synapses cause spine instability, in agreement with the described contribution of abnormal expression of GluA2-lacking Ca2+-permeable AMPARs in neurodevelopmental disorders." (PMID 34035473, 2021).
tumor (3 papers, 2013 to 2025). "Additional research has indicated that Rab39B is linked to the tumor microenvironment and the outlook of pancreatic adenocarcinoma." (PMID 40177653, 2025). "The ROC curve shows that RAB39B can distinguish between tumor cells and normal cells, and the expression of RAB39B is significantly correlated with the survival rate of AML patients." (PMID 40177653, 2025). "The GSE9327 dataset from the GEO database also showed a significant increase of RAB39B in DLBCL tumor tissues compared with normal control." (PMID 35910358, 2022). "In summary, we are the first to analyze the relationship between RAB39B expression and tumor immune infiltrate, m6A modification, ceRNA network, drug sensitivity, and prognosis in DLBCL." (PMID 35910358, 2022). "AML exhibited elevated expression of RAB39B in diverse tumor types." (PMID 40177653, 2025). "From this, we can foresee the potential of RAB39B in tumor immunotherapy." (PMID 40177653, 2025).
movement disorder (1 paper, 2017). Neurological conditions resulting in abnormal voluntary or involuntary movement, which may impact the speed, fluency, quality and ease of movement. "The DECIPHER and ISCA databases contain descriptions of female carriers of RAB39B CNVs who have developmental phenotypes including ID, but none of those described has a movement disorder." (PMID 29152164, 2017).
RAB39B also shares sentences with these, for which no sentence is quoted: infection (2 papers); 22q11.2 deletion syndrome (1); Alexander disease (1); Alzheimer disease (1); Angelman syndrome (1); behavioral disorders (1); bladder urothelial carcinoma (1); cardiovascular disease (1); Charcot-Marie-Tooth disease (1); Charcot-Marie-Tooth disease type 2B (1); cognitive disorder (1); colon adenocarcinoma (1); Cornelia de Lange syndrome (1); Creatine deficiency syndrome (1); DOORS syndrome (1); endothelial dysfunction (1); FRAXE syndrome (1); frontotemporal dementia (1); germ cell tumor (1); head and neck squamous cell carcinoma (1); juvenile neuronal ceroid lipofuscinosis (1); kidney chromophobe (1); lung adenocarcinoma (1); lung squamous cell carcinoma (1); neuroblastoma (1); neurological disorders (1); Pan (1); prostate adenocarcinoma (1); rectum adenocarcinoma (1); Rett syndrome (1).
A further 4 diseases each share a sentence with RAB39B in 1 paper.